BRAF (B-Raf proto-oncogene, serine/threonine kinase)
Diseases named in the same sentence as BRAF in open-access papers (continued):
Sharing a sentence is not in itself a finding about the gene and the disease.
melanoma (continued). "Interestingly, lj‐2‐66 also played a similar role in BRAF inhibitor‐resistant melanoma cells." (PMID 35332658, 2022). "V600K BRAF mutated melanoma patients were not analysed as a single subgroup." (PMID 35160279, 2022). "Therefore, to mimic the clinical scenario, we conducted a long-term clonogenic survival assay using GSK343 (targeting EZH2), JQ1 (targeting BET family BRD proteins-BRD2 and BRD3), TP-472 (targeting BRD7/9) using multiple BRAF mutant melanoma cell lines (M14, SKMEL-28, A375, and A2058)." (PMID 34771678, 2021). "Thus, our study also provided a potential treatment strategy, i.e., a combination of PYK2 inhibitor PF562271 with the BRAF inhibitor, vemurafenib, that may be an effective therapy to prolong the survival of patients with vemurafenib resistant melanomas." (PMID 34570440, 2021). "In melanoma, several distinct phenotypic states have been identified with a variety of microenvironmental cues, including hypoxia, nutrient limitation, BRAF inhibition, inflammation and immunotherapy, able to induce cells to dedifferentiate and become invasive and therapy-resistant." (PMID 33789714, 2021). "According to the data published by the TCGA network based on whole exome sequence analysis of patients with primary and/or metastatic melanoma, melanoma could be classified into four genomic subtypes: mutant BRAF, mutant RAS, mutant NF1, and Triple-WT (wild-type)." (PMID 34035810, 2021). "Thus, RND3‐RhoA signaling presents a possible compensatory mechanism in wild‐type BRAF and BRAFV600‐mutant melanoma cells treated with a BRAF inhibitor, suggesting that it could be a potential drug target in combination with WNT5A interference." (PMID 33969605, 2021). "In vivo melanoma models relied on mouse models such as tumor xenografts in immunocompromised mice, genetically engineered mice with conditional melanocyte-specific expression of the BRAF V600E oncogene, or mice with induced expression of the BRAF V600E oncogene by topical application of tamoxifen." (PMID 33539342, 2021). "Also, a recent paper showed that BRAF-mutant melanoma brain metastasis could be prevented by suppressing mitochondrial respiration." (PMID 34064489, 2021). "Since the free Ca2+ ion level is an important modulator of actin cytoskeletal dynamics, the goal of the present study was to investigate whether PMCA4b, by controlling intracellular Ca2+ levels, acts through the actin cytoskeleton in reducing motility of BRAF mutant melanoma cells." (PMID 33802790, 2021). "Therefore, BRAF-mutant melanomas are addicted to ketogenesis." (PMID 34924562, 2021). "However, in spite of the molecular similarities between melanoma and colorectal cancers, BRAF inhibitors have experienced opposite results with improved survival in patients with melanoma and significant resistance in colorectal cancers, suggesting drastic mechanistic differences." (PMID 33507915, 2021). "Taken together, despite the fact that this is only a case series, the detailed characterization of the impact of BRAF/MEK inhibition on tumor infiltrating lymphocytes allows an improved understanding of the underlying immunological and molecular mechanisms of targeted therapy in melanoma." (PMID 33275172, 2021). "Therefore, vemurafenib exhibited from partial to complete response in BRAF-mutated melanoma patients, and no response in patients with the wild-type BRAF gene." (PMID 34683910, 2021). "Therefore, it might be a favorable regime to combine a BRAF inhibitor with an inhibitor of the PI3K-AKT like Octpep-1 or MAPK pathway in BRAF melanoma patients." (PMID 33672955, 2021). "Moreover, NRAS-mutant melanoma, which constitutes ~25% of all melanoma cases, do not significantly benefit from those therapies, as they commonly lack oncogenic BRAF mutations and show a high degree of intrinsic resistance to MEKi." (PMID 34299213, 2021).
melanoma (continued). "Approximately 20% of melanoma patient tumors harbor mutations in the neuroblastoma RAS viral oncogene homolog (NRAS), 60% have a mutually exclusive mutation to NRAS in the v-raf murine sarcoma viral oncogene homolog B1 (BRAF), and 31% have mutation in the phosphoinositide 3-kinase (PI3K) pathway." (PMID 34092233, 2021). "Non-CSID melanoma is found in areas that are intermittently sun-exposed, in patients who are younger than 55 years old, melanomas with moderate mutational burden and are dominated by BRAF V600E mutations suggesting that they originate from nevi." (PMID 34359771, 2021). "Inhibition of the PI3K/AKT may reactivate the sensitivity of melanoma cells to a BRAF inhibitor." (PMID 34063141, 2021). "Several studies in patients with brain metastases from BRAF-mutant melanoma showed higher response rates with dabrafenib compared to vemurafenib, suggesting that the former might better penetrate the blood-brain barrier (BBB) with respect to the latter, thanks to its smaller size." (PMID 34804975, 2021). "Thus, via a data-driven and bottom-up modelling approach, the in silico model developed in this study can be built upon to simulate how BRAF-MEK-ERK inhibition affects not only intracellular ERK activity but also the progression of drug resistance in melanoma tumours." (PMID 34621046, 2021). "Previous studies showed BRAF inhibitors (e.g. vemurafenib and dabrafenib) and MEK inhibitors (e.g. trametinib and cobimetinib) have been shown to be efficient in providing rapid tumor response, prolonging progression-free survival, and bettering OS in BRAF V600-mutated melanoma." (PMID 34446007, 2021). "In addition, we also analyzed the gene expression data from a second cohort of matched tumor samples of 8 melanoma patients obtained prior to and during treatment with the BRAF inhibitors dabrafenib or vemurafenib alone or in combination with the MEKi trametinib (GSE99898)." (PMID 34165921, 2021). "Moreover, dependence on glycolysis sensitizes melanoma cells to the effects of BRAF inhibition." (PMID 33741961, 2021). "Next-generation sequencing (NGS) is a technology with higher sensitivity but also with higher costs and longer TAT compared to allele-specific tests, whose application in melanoma patients should be limited to those cases displaying a negative result with allele-specific BRAF exon 15 V600E/K PCR." (PMID 33801689, 2021). "Furthermore, in a series of 43 melanoma short-term cultures, we showed that the RICTOR locus was amplified in 19 out of 43 melanoma cell lines (44%) and that amplification was independent of the BRAF and NRAS mutation status." (PMID 34680615, 2021). "Thus, it is possible that V600E hotspot mutation on BRAF leads to more than one NRASP29S mutation, which can induce different physiological functions in response to LysoPS, leading to increased serum PS-PLA1 levels in melanoma patients." (PMID 33723350, 2021). "Moreover, visfatin may take part in the emergence of resistance to BRAF inhibitors by melanoma cells because the NAD level was rising during resistance development." (PMID 34068679, 2021). "In 2020, the first triple-therapy combining BRAF/MEK targeted and anti-PD-1 immunotherapy with atezolizumab, vemurafenib and cobimetinib was approved for unresectable or metastatic BRAF V600-mutated melanoma (IMspire150 study), while another trial investigating triple therapy missed its endpoint." (PMID 33435389, 2021). "However, the clinical correlates of BRAF and NRAS mutations in melanoma BM are limited." (PMID 33578810, 2021). "Therefore, when considering choice of adjuvant systemic therapy in BRAF mutant melanoma patients, clinicians should consider TT as an option that may not diminish the chance of response to subsequent IT." (PMID 33087895, 2021).
melanoma (continued). "Indeed, we detected the RAS–RICTOR interaction not only in resistant cells but also in biopsies of melanoma patients with resistance to BRAF-inhibition, and showed that disruption of the mTORC2–RAS interaction using JR-AB2-011 impeded the proliferation of resistant cells." (PMID 34680615, 2021). "Moreover, it expresses BRAF in its most frequent status in melanoma (mutBRAFV600E)." (PMID 33916029, 2021). "Moreover, activation of AHR was reported to promote resistance to BRAF inhibitors in melanoma." (PMID 32767816, 2021). "Notably, it seems that NRAS-mutant melanoma could be particularly sensitive to the combined CDK4/6/BRAF/MEK inhibition." (PMID 34071228, 2021). "Interestingly, these differential expressions were independent of the status of key melanoma mutations including BRAF, NF1, RAS mutations and triple wild type using GEPIA database." (PMID 34809598, 2021). "Different dermoscopic patterns (eg, blue-white veil, ulceration, peppering) have been identified as significant predictors of BRAF mutational status and SLN status, and therefore could be of great significance in making diagnostic-therapeutic algorithms for melanoma patients." (PMID 33954019, 2021). "Indeed, elevated OXPHOS has been identified in 30–50% of BRAF-mutant melanomas with both de novo and acquired resistance to MAPK pathway inhibitors; importantly, inhibition of mitochondrial biogenesis and function eradicated intrinsically resistant cells and improved efficacy of MAPKi." (PMID 34830962, 2021). "Thus, Lelliott and collaborators used a syngeneic BRAF V600E Cdkn2a-/-Pten-/- melanoma model and demonstrated that a triple therapy including BRAF, MEK, and CDK4/6 inhibitors led to an immediate tumor regression and improved mice survival, compared to the respective monotherapies." (PMID 34831311, 2021). "Notably, a decrease in cell proliferation was observed in cells treated with the combination of oligomycin and palbociclib compared to palbociclib alone, indicating that inhibition of mitochondrial metabolism can increase the sensitivity of BRAF mutant melanoma cells to palbociclib." (PMID 33572972, 2021). "In addition, less than 20% of patients with BRAF-mutated melanoma present intrinsic resistance and do not respond to BRAFi." (PMID 33478111, 2021). "Non-CSD-associated melanomas encompass acral and mucosal melanomas that usually do not show BRAF, NRAS, or NF1 mutations (triple wild-type), but in a subset may have KIT or SF3B1 mutations." (PMID 34571969, 2021). "Though there are several therapeutic approaches used in the treatment of melanoma, including targeting PD-L and BRAF kinase with V600E or V600D mutation, there is still no effective drug targeting all subtypes of skin melanoma nor ocular or mucosal melanoma or primary melanoma found in other organs." (PMID 34440617, 2021). "This mutation is most common in melanoma, where 50% of IPM might harbor a BRAF mutation." (PMID 35008185, 2021). "Disruption of redox balance could modulate the effects of BRAF-inhibition in melanoma cells." (PMID 33451139, 2021). "Thus, dabrafenib may represent a valid alternative to vemurafenib both in HCL patients naive to a BRAF inhibitor and in those previously intolerant to vemurafenib (as shown in melanoma patients)." (PMID 33731847, 2021). "Importantly, the high sensitivity, specificity, and AUC in BRAF-MUT advanced melanoma samples suggested that PLA1A could be used as a marker for an effective prediction of advanced BRAF-mutant melanoma cancer." (PMID 33723350, 2021). "However, in melanomas arising on mucosal surfaces or non-sun-exposed skin, BRAF mutations are infrequently reported." (PMID 34102999, 2021). "Overall, our current study reveals that bilirubin is a microenvironmental factor that can inhibit the activity of vemurafenib via reactivation of the ERK1/2-MNK1 signaling, which may help to develop new anti-tumor strategies in patients with BRAF mutant melanoma." (PMID 34222023, 2021).
melanoma (continued). "Furthermore, the W9 antibody could increase and restore sensitivity to v-raf murine sarcoma viral oncogene homolog B1 (BRAF) inhibitors in BRAFV600E melanoma cells that have acquired BRAF inhibitor resistance due to PDGFRα upregulation." (PMID 33802964, 2021). "Novel therapeutic approaches targeting genetic mutations in BRAF, MEK, RAS family of proteins, c-KIT, c-Met, VEGFR, and PI3K have been illustrated and implicated in the reduction of cell proliferation and cell survival in melanoma as well other forms of cancer." (PMID 33807778, 2021). "Importantly, remodeling of the actin cytoskeleton was demonstrated in BRAFV600E mutant melanoma cells with acquired resistance to BRAF inhibitor vemurafenib, and depletion of TESK1, a kinase that regulates actin cytoskeleton dynamics and reversed resistance to vemurafenib." (PMID 34201061, 2021). "Therefore, the standard treatment of NRAS-mutant patients is currently the same as for BRAF wild-type melanoma; anti-PD-1 based immunotherapy is the first-line therapy, and the second-line therapy includes anti-CTLA-4, cytotoxic chemotherapy, or drugs in experimental trials." (PMID 33530579, 2021). "Conversely, despite having an adequate reading depth, small-sized panels are applicable mainly in scenarios where the genomic regions of interest are known or anticipated (eg, BRAF mutation in BRAF mutant melanomas) but are not comprehensive enough to be useful in an unselected scenario." (PMID 34056539, 2021). "However, this alone does not explain the development of melanoma since BRAF mutations have been widely reported in benign melanocytic nevi, which do not necessarily transform into melanoma." (PMID 34680367, 2021). "Interestingly, 20–30% of NF1 deletions have been found in BRAF and NRAS wild type melanomas suggesting that NF1 may be implicated in MAPK pathway activation." (PMID 34680938, 2021). "Similarly, melanoma cancers that are no longer responsive to BRAF inhibition due to mutations can be resensitized by adding MEK inhibitors to the treatment regimen." (PMID 34461089, 2021). "Consequently, we examined whether its combination with other inhibitors would be a more effective therapeutic approach against BRAF (V600E) melanoma cells." (PMID 33672955, 2021). "Immunotherapy is continuously revolutionizing outcome in patients with melanoma, making noninvasive and highly effective local treatments for brain metastases more relevant, even if the benefits and risks of the combination of radiotherapy with BRAF-targeted agents are also yet to be established." (PMID 33993415, 2021). "Therefore, overall survival in Chinese patients with unresectable or metastatic BRAF V600-mutant melanoma administered the dabrafenib plus trametinib regimen remains unknown." (PMID 34504796, 2021). "Moreover, this combination can eliminate BRAF inhibitor-resistant melanoma cells." (PMID 34944799, 2021). "Notably, our results suggest connections between SOX10 and BRAF in the etiology of skin cancer and modulating their shared DDPs via chemotherapeutics might open a new avenue to rescue resistance to BRAF/MEK inhibitors in melanoma patients." (PMID 33842927, 2021). "In addition to the complex decision between monotherapy and combination therapy, approximately half of patients have to consider yet another treatment option, as targeted therapy with BRAF and MEK inhibitors can also be used in the presence of a BRAF mutation (up to 50% of melanomas)." (PMID 33879219, 2021). "For RUNX1 we could not prove a posttranscriptional regulation by miR-129-5p in BRAF associated melanoma (data not shown)." (PMID 34063443, 2021).
melanoma (continued). "Moreover, PLA1A had the highest sensitivity, specificity, and AUC in BRAF-MUT advanced melanoma samples, suggesting that PLA1A could be used as a marker for an effective prediction and diagnosis of advanced BRAF-mutant melanoma cancer." (PMID 33723350, 2021). "Furthermore, adding FGF1 inhibitors to the combination may resensitize melanomas to BRAF/MEK inhibitors." (PMID 33807778, 2021). "The main oncogenic mutation of BRAF occurs when the valine amino acid in position 600 is replaced by glutamic acid to produce V600EBRAF, which is the major mutation in melanomas and papillary thyroid carcinomas, accounting for up to 63% in melanoma and 50% in papillary thyroid carcinomas." (PMID 34638829, 2021). "Importantly, this novel dPCR assay could be extended to identify BRAF V600E status in biopsies from other types of cancer, such as melanoma, non–small cell lung cancer, colon cancer, colorectal cancer, and ovarian cancer, in the context of precision medicine." (PMID 34613404, 2021). "Another combination of afatinib with crizotinib (a MET inhibitor) showed efficacy, was proposed as a promising alternative targeted therapy option for melanoma irrespective of BRAF/NRAS mutational status, and may overcome resistance to BRAF inhibitors." (PMID 33918490, 2021). "In contrast to monotherapy, we also observed that intermittent drug (combination of ENCO+BINI) dosing might not be beneficial for melanoma patients with a BRAF mutation." (PMID 34885166, 2021). "Interestingly, BRAF was not the most common mutation in the melanoma samples tested by the IMPACT panel but the TERT hot spot promoter mutation appeared with a frequency of 73%." (PMID 34109763, 2021). "In contrast, in melanoma cells with activated BRAF, it is possible that constitutive activation of PI3K may facilitate senescence bypass through the same mechanism, increasing capacity for protein synthesis to meet the demands of proliferation driven by constitutive MAPK signaling." (PMID 34819350, 2021). "To support the discovery of new drug candidates for melanoma, we examined 180 metabolic modulators, including phytochemicals and anti-diabetic compounds, for their growth-inhibitory activities against melanoma cells, alone and in combination with the BRAF inhibitor vemurafenib." (PMID 33623106, 2021). "Hence, targeting MITF in combination with BRAF or cyclin-dependent kinase may offer a rational therapeutic way on melanoma." (PMID 34289891, 2021). "In phase 3 clinical trials, the anti-PD-1 antibodies nivolumab and pembrolizumab, respectively, demonstrated an improved OS compared to ipilimumab in advanced melanoma patients regardless of the BRAF mutation status and as a consequence constitute a front-line standard of care." (PMID 33530393, 2021). "Furthermore, mutations in the citric acid cycle enzymes isocitrate dehydrogenases 1 and 2 could confer a growth advantage in melanoma cells with mutant BRAF." (PMID 34831420, 2021). "Biopsies of the lung mass revealed melanoma without BRAF V600 mutations (BRAF wild-type), resulting in the diagnosis of stage IV melanoma with unknown primary." (PMID 34956219, 2021). "LDH levels were correlated with clinical response in two out of five patients, and the number of CTCs seemed to reflect the response in four out of five patients, suggesting that CTC count could be a useful biomarker for advanced melanoma treated with BRAF/MEK inhibitors." (PMID 33731038, 2021). "Available systemic treatments for patients with advanced melanoma include monoclonal antibodies, such as nivolumab that targets programmed cell death protein 1, and ipilimumab, which targets cytotoxic T-lymphocyte antigen-4, as well as oral small-molecule drugs that inhibit BRAF or MEK proteins." (PMID 34063139, 2021).